SPRED2 (sprouty related EVH1 domain containing 2)
Description:
Negatively regulates Ras signaling pathways and downstream activation of MAP kinases. Recruits and translocates NF1 to the cell membrane, thereby enabling NF1-dependent hydrolysis of active GTP-bound Ras to inactive GDP-bound Ras. Inhibits fibroblast growth factor (FGF)-induced retinal lens fiber differentiation, probably by inhibiting FGF-mediated phosphorylation of ERK1/2 (By similarity). Inhibits TGFB-induced epithelial-to-mesenchymal transition in lens epithelial cells (By similarity).
Synonyms: Spred-2; FLJ21897; FLJ31917; NS14
Tractability: Small molecule: a structure with a bound ligand is known. Antibody: UniProt places it where antibodies can reach, with high confidence; its Gene Ontology location is reachable by antibodies, with medium confidence. PROTAC: UniProt records ubiquitination sites on it; ubiquitination databases record sites on it.
Gene: Protein-coding gene on chromosome 2 (65,310,851 to 65,432,637, reverse strand). Ensembl gene ENSG00000198369.
Subcellular location: Cell membrane; Cytoplasmic vesicle, secretory vesicle membrane; Cytoplasm
Subcellular location (Human Protein Atlas): Nucleoplasm; Cytosol
Pathways (Reactome):
Signal Transduction: FGFRL1 modulation of FGFR1 signaling; Regulation of RAS by GAPs
Disease: RAS signaling downstream of NF1 loss-of-function variants
Gene Ontology:
Molecular function: protein binding; protein kinase binding; protein serine/threonine kinase inhibitor activity; stem cell factor receptor binding
Biological process: negative regulation of intracellular signal transduction; negative regulation of epithelial to mesenchymal transition; negative regulation of ERK1 and ERK2 cascade; negative regulation of lens fiber cell differentiation; negative regulation of MAPK cascade; negative regulation of transforming growth factor beta receptor signaling pathway; regulation of signal transduction
Cellular component: cytoplasm; cytosol; plasma membrane; cytoplasmic vesicle; membrane; transport vesicle membrane
Genetic constraint (gnomAD): Loss-of-function variants: 42 observed, 39.93 expected, observed/expected ratio (o/e) 1.05, 90% interval 0.82 to 1.36. The upper end of that interval is the gene's LOEUF score, 1.36, which puts it in group 5 of 6, group 1 being the genes least tolerant of losing a copy. Missense variants: 538 observed, 585.08 expected, observed/expected ratio (o/e) 0.92, 90% interval 0.86 to 0.99. Synonymous variants: 216 observed, 223.95 expected, observed/expected ratio (o/e) 0.96, 90% interval 0.86 to 1.08.
Homologues: Orthologues: pig SPRED2 (98% identical), macaque SPRED2 (98% identical), rabbit SPRED2 (98% identical), chimpanzee SPRED2 (98% identical), dog SPRED2 (95% identical), guinea pig SPRED2 (95% identical), rat Spred2 (92% identical), mouse Spred2 (92% identical), tropical clawed frog spred2 (74% identical), zebrafish spred2b (68% identical), zebrafish spred2a (67% identical), Drosophila melanogaster Spred (35% identical), and 2 more. Paralogues in human: SPRED1 (55% identical), SPRED3 (39% identical), ENAH (20% identical), VASP (17% identical), EVL (17% identical).
Diseases named in the same sentence as SPRED2 in open-access papers:
SPRED2 is named in the same sentence as 60 diseases in open-access papers, as found by Europe PMC text mining. Sharing a sentence is not in itself a finding about the gene and the disease. The quoted sentences say what the papers report.
hepatocellular carcinoma (10 papers, 2015 to 2024). A malignant tumor that arises from hepatocytes. "In the past, SPRED2 has been linked to drug resistance and described as a potential prognostic marker for multiple cancer types such as chronic myeloid leukemia, prostate cancer, and hepatocellular carcinoma." (PMID 35205702, 2022). "To investigate a potential association between SPRED2 and autophagy in HCC, we initiated our analysis using data from The Cancer Genome Atlas (TCGA)–Liver Hepatocellular Carcinoma (LIHC) database." (PMID 38892460, 2024). "SPRED2 can regulate the proliferation and apoptosis of chronic myelogenous leukemia and hepatoma cells and inhibit the growth of tumors by inhibiting the RAS/MAPK pathway." (PMID 38402263, 2024). "Here, we investigated the effects of SPRED2 loss on hepatocellular carcinoma (HCC) cell function." (PMID 36902429, 2023). "In colorectal cancer and hepatocellular carcinoma, SPRED2 can inhibit the epithelial-to-mesenchymal transition and cell motility." (PMID 35205702, 2022). "Decreased expression of Spred2 is observed in hepatocellular carcinoma and prostate cancer, while forced Spred2 expression suppresses cell growth in a variety of tumor cells." (PMID 27028858, 2016). "Expression of Spred1 and/or Spred2 was frequently reduced in hepatocellular carcinoma and prostate cancer, while decreased Spred levels were associated with increased tumor invasion and metastasis." (PMID 27028858, 2016). "Here, we aimed to determine whether SPRED2 plays a role in autophagy in hepatocellular carcinoma (HCC) cells." (PMID 38892460, 2024). "Interestingly, Spred2 expression is down-regulated in invasive carcinomas such as hepatocellular carcinoma and prostatic adenocarcinoma." (PMID 34818323, 2021). "Downregulation of SPRED2 was reported in prostate cancer and hepatocellular carcinoma." (PMID 26254226, 2015). "Previous studies demonstrated that Spred2 mRNA expression was decreased in hepatocellular carcinoma (HCC) and prostatic adenocarcinoma, comparing with that in adjacent non-tumor tissue and benign gland, respectively." (PMID 34818323, 2021). "SPRED2, a negative regulator of the MAPK signal-transduction pathway, is frequently downregulated in cancers such as hepatocellular carcinoma and prostate cancer." (PMID 35205702, 2022). "Further studies are necessary to investigate the contribution of Spred2 in development of NAFLD/NASH, and subsequent hepatocellular carcinoma." (PMID 30723473, 2019).
colorectal cancer (8 papers, 2019 to 2024). A primary or metastatic malignant neoplasm that affects the colon or rectum. "For example, METTL3 expression is elevated in breast cancer tissues and cells and can promote the multiplication of breast cancer cells and inhibit apoptosis by targeting Bcl-2; METTL3 upregulation promotes the metastasis of colorectal cancer cells through miR-1246/SPRED2/MAPK signaling pathway." (PMID 33818282, 2021). "In colorectal cancer, Peng showed that METTL3 affects the ERK pathway by regulating the miR-1246/SPRED2 signaling axis and enhancing the invasion ability of cancer." (PMID 37095108, 2023). "In human colorectal cancer, up-regulation of METTL3 can promote the metastasis of colorectal cancer cells via the miR-1246/SPRED2/MAPK pathway." (PMID 35794583, 2022). "Similarly, the overexpression of METTL3 in colorectal cancer leads to abnormal m6A modification, and further promotes tumor progression and metastasis via its targets SOX2 and the METTL3/miR-1246/Sprouty-related EVH1 domain containing 2 (SPRED2) axis, respectively." (PMID 32709063, 2020).
breast carcinoma (7 papers, 2021 to 2025). "Treatment of SPRED2-deficient breast cancer cells with a combination of the ERK 1/2 inhibitor ulixertinib and 4-hydroxytamoxifen (4-OHT) can inhibit cell growth and proliferation and overcome the induced tamoxifen resistance." (PMID 35205702, 2022). "SPRED2 appears to activate autophagy by interacting with selective autophagic components, such as LC3, p62, a neighbor of breast cancer susceptibility gene I (BRCA1) and cathepsin D, as evidenced by co-immunoprecipitation of these molecules with SPRED2." (PMID 38892460, 2024). "In the present study, we found that SPRED2 is downregulated in a large proportion of breast-cancer patients." (PMID 35205702, 2022). "Here, we investigated the functional relationship between NF and SPRED2 in breast cancer (BC)." (PMID 41155378, 2025). "We found that SPRED2 deficiency causes a hyperactivation of the mitogen-activated protein kinases (MAPKs) ERK1/ERK2, which in turn enhances estrogen signaling and diminishes the toxic effects of tamoxifen on breast cancer cells." (PMID 35205702, 2022). "Moreover, the knockdown of SPRED2 significantly increases cell proliferation and leads to tamoxifen resistance of breast-cancer cells that are initially tamoxifen-sensitive." (PMID 35205702, 2022). "Taken together, these results indicate that SPRED2 may also be a tumor suppressor for breast cancer and that it is a key regulator of cellular sensitivity to 4-OHT." (PMID 35205702, 2022). "Enrichment difference analysis of the genes showing changes after OHT treatment revealed known breast cancer oncogenes such as HDAC3, UBE2C and CPSF7 among the depleted genes and reported breast cancer suppressors such as CSK, SPRED2 and TSC2 among the enriched genes." (PMID 38914552, 2024).
prostate carcinoma (7 papers, 2015 to 2022). A carcinoma that arises from epithelial cells of the prostate gland. "Only one report exists with regard to SPREDs in prostate cancer, describing evidence for a loss of SPRED2 expression in high Gleason grade lesions." (PMID 26075267, 2015). "Down-regulated Spred2 expression was particularly evident in higher grade prostate cancers, and Spred2 expression levels in HCC tissue were inversely correlated with the incidence of tumor invasion and metastasis." (PMID 34818323, 2021). "Similarly, in both datasets assessed here, SPRED2 expression is significantly suppressed in prostate cancer tissues." (PMID 26075267, 2015).
lung carcinoma (4 papers, 2016 to 2022). "Here we show that Spred2 induces caspase-independent but autophagy-dependent cell death in human cervical carcinoma HeLa and lung cancer A549 cells." (PMID 27028858, 2016). "TBX5, SPRED2, and NKX2-1 have been shown to exhibit tumor suppressor functions in lung cancer, while GMIP function has yet to be determined in cancer cells." (PMID 33227088, 2020). "This microRNA is capable of promoting lung cancer by subexpressing several regulators (SPRED1, SPRED2, SPRY1, RASA1, SPRY3 and SPRY4) in RAS / MAPK signaling, which leads to an increase in the signaling of this pathway." (PMID 29053755, 2017).
Noonan syndrome (4 papers, 2023 to 2025). Noonan Syndrome (NS) is characterized by short stature, typical facial dysmorphism and congenital heart defects. "Notably, biallelic LoF variants in SPRED2 underlie a recessive form of Noonan syndrome (NS; MIM: PS163950)." (PMID 40362579, 2025). "The homozygous Leu100Pro amino acid substitution in SPRED2, a protein negatively controlling RAS function, has recently been identified to be causally linked to a recessive form of Noonan syndrome." (PMID 40362579, 2025). "Recently, SPRED2 was recognized as a novel Noonan syndrome gene with autosomal recessive inheritance, and only four families have been described to date." (PMID 38254922, 2023).
RASopathy (4 papers, 2019 to 2022). Developmental syndromes caused by germline mutations (or in rare cases by somatic mosaicism) in genes that alter the Ras subfamily and mitogen-activated protein kinases that control signal transduction. "Indeed, the defective function of an increasing number of proteins (i.e., neurofibromin, LZTR1, SPRED1 and SPRED2) provides evidence of multiple circuits implicated in the negative control of RAS function as a recurrent theme of RAS‐MAPK signaling upregulation in RASopathies." (PMID 36394128, 2022). "The recessive inheritance of this new RASopathy further indicates a differential requirement of SPRED2 and SPRED1 function in developmental processes." (PMID 36394128, 2022). "Interestingly, a recent report described a case series of patients with an autosomal-recessive NS-like phenotype resulting from loss of SPRED2 function, further validating SPRED2 as a RASopathy gene." (PMID 35178568, 2022).
Anxiety (2 papers, 2020). Intense feelings of nervousness, tension, or panic often arise in response to interpersonal stresses. "Notably, similar decrement of anxiety was also found in a SPRED2-deficient mouse model of obsessive compulsive disorder (OCD)." (PMID 32390810, 2020).
colitis (2 papers, 2016 to 2020). Inflammation of the colon. "Interestingly, Spred2 KO mice were resistant to dextran sulfate sodium (DSS)-induced acute colitis as indicated by lower levels of body weight loss and disease activity index." (PMID 27869219, 2016). "In the present study, we demonstrated that Spred2 KO mice were resistant to DSS-induced acute colitis; however, it remains unclear how Spred2-deficincy results in the resistance to DSS-induced colitis." (PMID 27869219, 2016). "Our results obtained using Spred2 KO mice suggest that inhibition of Spred2 may be useful to prevent severe colitis and subsequent colon cancer; thus, Spred2 may be a new therapeutic target for the treatment of UC." (PMID 27869219, 2016). "Interestingly, Spred2 KO mice were less sensitive to DSS-induced acute colitis than WT mice and developed a fewer number of tumors in a chemically induced colon cancer level." (PMID 27869219, 2016).
diabetes (2 papers, 2021 to 2024). "Conclusion: miR-142-3p promotes the development of diabetes by inhibiting SPRED2-mediated autophagy, including inducing cell apoptosis, aggravating cellular oxidative stress and secretion of inflammatory factors, and resveratrol improves this effect." (PMID 33621197, 2021). "We inferred that miR-142-3p may inhibit SPRED2-mediated autophagy Level, and then induce cell apoptosis, aggravate cell oxidative stress and inflammatory factor secretion, and ultimately promote the development of diabetes." (PMID 33621197, 2021). "This SNP is also associated with levels of methylation in SPRED2 in GoDMC datasets, along with many other SNPs in the same gene, which could suggest that the differential methylation we observe is due solely to genetic variation between individuals with diabetes and those without." (PMID 38574408, 2024).
Insulin resistance (2 papers, 2019 to 2024). Increased resistance towards insulin, that is, diminished effectiveness of insulin in reducing blood glucose levels. "In conclusion, we showed that Spred2-deficiency promotes obesity, adipose tissue inflammation, and insulin resistance, possibly via enhanced adipose tissue inflammation caused by enhanced macrophage activation." (PMID 30723473, 2019). "This is of particular note due to SPRED2 having been identified as a potential therapeutic tool for the prevention of insulin resistance." (PMID 38574408, 2024). "Exacerbated adipose tissue inflammation in Spred2 KO mice led to aggravated insulin resistance and fatty liver disease." (PMID 30723473, 2019). "Taken together, these results suggested that Spred2, in macrophages, negatively regulates high fat diet-induced obesity, adipose tissue inflammation, metabolic abnormalities, and insulin resistance by inhibiting the ERK/MAPK pathway." (PMID 30723473, 2019). "Thus, Spred2 represents a potential therapeutic tool for the prevention of insulin resistance and resultant metabolic syndrome." (PMID 30723473, 2019). "Consequently, in vivo metabolic tests were performed, which showed that both glucose intolerance and insulin resistance were aggravated in Spred2 KO mice when compared with WT mice." (PMID 30723473, 2019). "Increased serum lipid levels and impaired insulin resistance may cause non-alcoholic fatty liver disease (NAFLD)/non-alcoholic steatohepatitis (NASH) in Spred2 KO mice." (PMID 30723473, 2019). "A knockout mice study showed that removal of SPRED2 increased insulin resistance from a high fat diet suggesting SPRED2 to be a negative regulator of insulin resistance via its suppression of the ERK/MAPK pathway." (PMID 38574408, 2024).
invasive carcinoma (2 papers, 2021 to 2023). A carcinoma that is not confined to the epithelium, and has spread to the surrounding stroma. "The expression of SPRED2 was previously shown to be downregulated in invasive carcinomas, including HCC." (PMID 36902429, 2023). "Thus, Spred2 may play a role as a tumor suppressor in non-invasive carcinomas, but the function appears to be lost in invasive carcinoma." (PMID 34818323, 2021). "In our study, Spred2 mRNA expression was increased in non-invasive cancer HGPUC, whereas the expression in invasive bladder cancer IUC was significantly decreased as compared to that in non-invasive carcinoma HGPUC." (PMID 34818323, 2021).
melanoma (2 papers, 2012 to 2019). A malignant, usually aggressive tumor composed of atypical, neoplastic melanocytes. "SPRED2 (Sprouty Related EVH1 Domain Containing 2) is a member of the Sprouty/SPRED family of proteins that regulate growth factor-induced activation of the MAPK cascade, an apoptosis enhancer in melanoma." (PMID 31117943, 2019).
osteosarcoma (2 papers, 2022 to 2024). A usually aggressive malignant bone-forming mesenchymal neoplasm, predominantly affecting adolescents and young adults. "In this case, miR-19 was upregulated in osteosarcoma cells, targeting SPRED2 and reducing its expression, which suppressed autophagy, ultimately promoting the proliferation and malignant transformation of osteosarcoma cells." (PMID 38486976, 2024). "An oncogenic miRNA, member of the miR-17-92 cluster, was upregulated in OS cells and negatively regulated SPRED2, thus promoting the malignant transformation of osteosarcoma cells." (PMID 35054891, 2022).
rheumatoid arthritis (2 papers, 2016 to 2023). A chronic, systemic autoimmune disorder characterized by inflammation in the synovial membranes and articular surfaces. "Another polymorphism in SPRED2 (rs934734) was associated with an elevated ESR in rheumatoid arthritis patients." (PMID 37238156, 2023). "Other loci containing alleles robustly associated with higher eosinophil count and increased risk of rheumatoid arthritis were COG6, SPRED2, RUNX1, and the highly pleiotropic ATXN2/SH2B3/BRAP region." (PMID 27863252, 2016).
Alzheimer disease (1 paper, 2024). A progressive, neurodegenerative disease characterized by loss of function and death of nerve cells in several areas of the brain leading to loss of cognitive function such as memory and language. "A recent Genome-wide association study suggested that SPRED2 is linked to Alzheimer's disease." (PMID 39510187, 2024).
atherosclerosis (1 paper, 2015). A disease characterized by the build-up of fatty material and calcium deposition in the arterial wall resulting in partial or complete occlusion of the arterial lumen. "Animal studies using a xenograft mice model and ApoE KO mice fed a high-fat diet further supported the link among oxLDL, miR-210, and SPRED2 in relation to tumorigenesis and atherosclerosis." (PMID 26254226, 2015).
bladder cancer (1 paper, 2021). "Our present study suggests that Spred2 functions to suppress the growth and progression of cancer in non-invasive bladder cancer through suppressing the ERK pathway, and this regulatory mechanism no longer functions in invasive bladder cancer." (PMID 34818323, 2021). "We examined Spred2 mRNA expression in bladder cancer database by Sanchez-Carbayo bladder 2 dataset, Blaveri bladder 2, and Stransky bladder in a public cancer microarray database (ONCOMINE)." (PMID 34818323, 2021). "Thus, the expression level of Spred2 mRNA can be clinically important for the prognosis of bladder cancer patients." (PMID 34818323, 2021). "However; the pathophysiological roles of Spred2 in bladder cancer tumorigenesis remain largely unknown." (PMID 34818323, 2021). "Thus, altered Spred2 expression could affect urothelial tumorigenesis by regulating the Ras/Raf/ERK-MAPK pathway in bladder cancer." (PMID 34818323, 2021).